TNF (tumor necrosis factor)
Diseases named in the same sentence as TNF in open-access papers (continued):
Sharing a sentence is not in itself a finding about the gene and the disease.
Hepatitis (continued). "Con A-induced hepatitis mimicsmany aspects of human acute liver failure, including severe damage by activated Tand natural killer T (NKT) cells.Con A-stimulated T cells produce TNF-α and TNF-α induces apoptosis in mouse hepatocytes bystimulating ROS production." (PMID 30426855, 2018). "Besides, hepatic macrophages can release many proinflammatory cytokines such as tumor necrosis factor-α (TNF-α), interleukin-1β (IL-1β), and IL-6 which may induce liver cellular apoptosis and aggravate liver inflammation." (PMID 29743924, 2018). "However, a recent publication reported that TNF-α does not directly induce hepatocyte death in ConA hepatitis in contrast to the d-GalN/LPS model." (PMID 27831558, 2016). "In this study we demonstrated that replication of LCMV-WE (but not LCMV-ARM) shared the hallmarks of arenavirus-induced hepatitis in non-human primates, namely elevated transaminase levels, strong up-regulation of TNF-α, and induction of liver cell proliferation." (PMID 25822203, 2015). "Thus, our data suggest that AR might mediate the production of TNF-α and IL-6 to influence the development of MCD diet-induced liver inflammation." (PMID 24066058, 2013). "Similarly, increased IL-1α levels in AVH-E vs recovery in the current series of patients and increased levels of IL-1β and TNF-α in AVH-E and recovered cases in our previous report suggest their probable role in the pathogenesis of hepatitis and hepatocytic injury." (PMID 22384080, 2012). "Moreover, we found that elevated levels of inflammatory cytokines (TNF-α and IL-1β) were positively correlated with serum enzymes (ALP, ALT, and AST) in IC group, which is further demonstrating the applicability of these enzymes in monitoring the liver inflammation." (PMID 30483393, 2018). "We confirmed a significant decrease in iNOS, COX2, IL-6, IL-1β, and TNF-α in AGF geese, and we found them to be involved in ileal permeability and ileal and liver inflammation in geese lacking pasture supplementation." (PMID 38003191, 2023). "The results showed that IL-1β and IL-6 levels were increased in the APKO-DEN hepatitis mice compared with WT-DEN mice, but the IL-12p70 and TNFα levels did not change significantly." (PMID 33558702, 2022). "We observed that SHP deficiency in hepatocytes led to the increased secretion of CXCL2, but not CXCL1, upon TNFα stimulation, emphasizing that hepatocytes contribute to increased levels of circulating CXCL2 in Shp KO mice during ConA-induced hepatitis." (PMID 30323351, 2018). "In both α-GalCer- and Con A-induced murine hepatitis models, CD160−/− mice suffered from severe inflammation with elevated IL-4, IL-6, IFN-γ, and TNF-α and could not fully recover from lethal Con A challenge." (PMID 31332204, 2019). "Interestingly, while TRAIL administration did not induce hepatitis in Ripk1LPC-KO mice or in their WT counterparts, its combination with IFN-γ only induced TNF-α dependent apoptosis in the Ripk1LPC-KO mice." (PMID 28835677, 2017). "As proinflammatory cytokines, IFN-γ and TNF-α, were both able to promote hepatitis through distinguished mechanisms, the maintenance of IFN-γ and TNF-α production in exhausted T cells could drive nonspecific immunoresponse to persistent inflammation." (PMID 25789969, 2015). "We have recently found that the TNF and FasL produced by liver CD11b+ Kupffer cells/Mφ are final effectors in CCl4-induced hepatic injury, while neither NKT cells nor NK cells are involved in this hepatitis." (PMID 26333171, 2015). "Furthermore, in CHB, IFNγ/TNF responses to brief PMA/Ionomycin stimulation in Vδ2+ γδT-cells correlated inversely with serum alanine aminotransferase (ALT), with persistent deficit in patients with hepatitis ALT flares compared to those without flares." (PMID 30998783, 2019).
Hepatitis (continued). "This last observation could explain why in the α-GalCer model, where TNF is involved in α-GalCer-induced upregulation of FasL on NKT cells, but hepatocyte damage depends mainly on FasL, CTSB inhibition did not protect against α-GalCer mediated hepatitis." (PMID 29541077, 2018). "Further analysis of such correlation in CHC groups revealed a positive correlation between TNF-α and apelin in cases of ASC but was nonsignificant after adjustment for covariants, emphasizing the role of covariants in the induction of apelin in early stages of hepatitis." (PMID 22007137, 2011).
Cachexia (367 papers, 1988 to 2026). Severe weight loss, wasting of muscle, loss of appetite, and general debility related to a chronic disease. "TNF-α, also known as cachectin, is a pro-inflammatory cytokine that plays a crucial role in cachexia, and its production is linked to muscle loss and systemic inflammation." (PMID 40869331, 2025). "Pro-inflammatory cytokines, notably tumor necrosis factor-alpha (TNF-α), interleukin-6 (IL-6), and interleukin-1 beta (IL-1β), significantly contribute to cachexia pathophysiology by promoting muscle wasting and fat loss." (PMID 40133874, 2025). "TNF-α, a cytokine known as a mediator of inflammation and tumor-associated cachexia, controls the concentration of ALB." (PMID 37505298, 2024). "Underlying the pathogenesis of cachexia are many inflammatory cytokines such as tumor necrosis factor‐alpha (TNF‐α), interleukin‐1beta (IL‐1β), and interleukin‐6 (IL‐6), which cause malnutrition and loss of skeletal muscle mass." (PMID 39229565, 2024). "Third, in patients with HF, cachexia can cause the generation of tumor necrosis factor (TNF), which is detrimental to the myocardium and induces inflammation." (PMID 39091358, 2024). "Injection of TNF-α into experimental animals induces anorexia, weight loss, and the development of cachexia; while preemptive administration of TNF-α antibody mitigated cancer cachexia manifested with significantly less weight loss and leg muscle preservation." (PMID 39114348, 2024). "Cancer cachexia is caused by anorexia, muscle atrophy, and increased energy consumption due to tumor necrosis factor-α and interleukin-69." (PMID 39468284, 2024). "The blood concentration of HMGB1, elevated in patients with cachexia, is associated with TNFα concentration and is well correlated with sarcopenia in skeletal muscle cancer." (PMID 39125651, 2024). "The authors found that the CC genotype was considered to have a higher risk of cachexia (p = 0.044; HR = 3.724) and that patients with the CC genotype had significantly lower body weight (p = 0.045) and higher TNF-α plasma levels (p = 0.006)." (PMID 37533569, 2023). "In many chronic inflammatory states, TNF-α induces cachexia, i.e., loss of muscle mass through catabolic processes." (PMID 35720419, 2022). "The authors found that the presence of the CC genotype of TNF-α was associated with a higher risk of developing cachexia." (PMID 35884467, 2022). "For example, TNFα is a strong mediator of CNS inflammation and is likely implicated in the brain-fat axis activation that triggers adipose tissue wasting in cachexia." (PMID 36158184, 2022). "Insulin resistance in patients with cachexia, as well as in murine models, has been associated with muscle wasting and is induced by TNF-α." (PMID 36072935, 2022). "For example, proinflammatory cytokines, such as TNF‐α, IL‐1, and IL‐6, promote the activation of transcription factors associated with muscle wasting and play a key role in the pathological mechanism of cachexia." (PMID 36105371, 2022). "This is supported by the observation that low levels of IL-10 together with high levels of TNF-α have been associated with anemia and cachexia." (PMID 36093199, 2022). "In the unconditional logistic regression analysis, individuals with TNF-α 308G/A mutant genotypes had a significantly increased risk of cachexia as compared with those with the wild genotype." (PMID 34900737, 2021). "Overall, unintentional weight loss, elevated blood levels of CRP, IL-6, IL-1β, TNFα, and muscle function decline should be assessed in any patient to diagnose cachexia independently from the underlying disease." (PMID 33445790, 2021). "C3a also stimulates the production of cachexia-associated inflammatory mediators such as TNF-α and IL-1." (PMID 34830921, 2021). "In both pancreatic and NSCL cancer cohorts, the mutant TNF-α variant of 308 G/A was positively associated with cachexia; on the contrary, that of 1031T/C was negatively associated with cachexia in the NSCL cancer patients." (PMID 34900737, 2021).
Cachexia (continued). "The most important role in CRC-associated cachexia is played by pro-inflammatory cytokines, including the tumor necrosis factor α (TNFα), originally known as cachectin, Interleukin (IL)-1, IL-6, and certain chemokines (e.g., IL-8)." (PMID 33557173, 2021). "Our results show that the mutant TNF-α variant of 308 G/A was significantly associated with increased risk of cachexia in both the pancreatic and NSCL cancer patients." (PMID 34900737, 2021). "Cytokines produced by immune or tumor cells, including TNF-α, IL-1β, and IL-6, have been proven to cause muscle atrophy in cachexia patients and animal models." (PMID 34093209, 2021). "Decreased capillary density is associated with poor prognoses of cachexia and is influenced by TNFα." (PMID 33445790, 2021). "On the other hand, individuals with TNF-α −1031T/C mutant genotypes had a significantly decreased risk of cachexia as compared with those with the wild genotype." (PMID 34900737, 2021). "TNF-α plays a direct role in cachexia, causing catabolic effects not only in muscles but also in AT through the inhibition of lipoprotein lipase, resulting in a loss of AT." (PMID 33557173, 2021). "Among the pro-inflammatory mediators, the ones mainly implicated in the pathogenesis of cachexia are TNF-α, IL-6, IL-1, IL-8, and IFN-γ." (PMID 34832866, 2021). "Several of these upstream regulators such as IL-1 alpha, IL4, IL6, LIF, TNF have known causal roles in cachexia validated using experimental models." (PMID 33334063, 2020). "Cancer cachexia is mainly caused by diminished oral intake and catabolic factors secreted by tumors, including interferon-gamma, interleukins, and tumor necrosis factor." (PMID 32083001, 2020). "Many in vivo studies have shown that the induction of an inflammatory state by TNF-α infusion initiate the development of cachexia, resulting in reduced food intake, loss of bodyweight, and skeletal muscle loss." (PMID 33329046, 2020). "We analyzed expression of several transcripts associated with cachexia, including C‐reactive protein (Crp), insulin‐like growth factor 1 (Igf‐1), IL‐1ß (Il‐1b), IL‐6 (Il‐6), and TNF (Tnf)." (PMID 32039522, 2020). "It has been reported that several pro-inflammatory cytokines including TNFα are associated with cachexia and anorexia in both humans and rodents." (PMID 31581569, 2019). "For instance, inflammatory markers like tumor necrosis factor-alpha (TNF-α) and interleukin-6 (IL-6) are linked to cachexia and known to contribute to muscle loss and lipid wasting by increased protein breakdown and adipocyte lipolysis." (PMID 31717736, 2019). "In mice, the peritoneal injection of cancer cells expressing TNFα has been shown to cause weight loss and cachexia." (PMID 30764482, 2019). "While TNFα is known to play a major role in cancer-associated cachexia in general, the loss of exocrine pancreas function is one of the main causes of malnutrition and weight loss in cases of PDAC." (PMID 30764482, 2019). "Inflammation is the driving force of cachexia, and the most commonly implicated proinflammatory cytokines in cachexia include tumor necrosis factor α (TNF-α), interleukin (IL) 1, IL-6, and IL-8." (PMID 31069007, 2019). "Numerous inflammatory cytokines are involved in the etiology of cachexia, including tumor necrosis factor alpha, interleukin (IL)-6, IL-1 and interferon gamma indicating that systemic inflammation plays a central role in cancer-associated cachexia." (PMID 31466311, 2019). "TNF-α is an important regulator of many types of immune cells, causing cell death or cachexia, a common condition suffered by TB patients that includes weight loss, fatigue, or general weakness." (PMID 29494546, 2018). "Patients with low miRNA expression are believed to be highly susceptible to cachexia, probably through the promotion of inflammatory response mediated by TNF-α." (PMID 30200243, 2018).
Cachexia (continued). "Toxoplasma cachexia is characterized by a loss of 20% in body mass, including fat and muscle, transient anorexia and an acute elevation in the hallmark cachexia cytokines IL-1, TNF and IL-6." (PMID 30379866, 2018). "SGA had a significant impacton the risk of cachexia only when it was accompanied by TNF-α analysis (OR = 5.958)." (PMID 30200243, 2018). "The aim of the study was the investigation of TNF-α −1031T/C as a cachexia risk factor as well as the assessment of the correlation between TNF-α −1031T/C and plasma TNF-α concentration in HNC patients." (PMID 29802455, 2018). "The significant role of the systemic inflammatory response mediated by TNF-α in the etiopathology of cachexia encourages investigating SNPs of TNF-α as cachexia related risk factors." (PMID 29802455, 2018). "When we analyzed the cachexia model with weight loss of >5% followed by high TNF-α level, the risk score significantly increased (OR = 88.0)." (PMID 30200243, 2018). "TNF-α has been implicated in wide range of cachexia- associated mechanisms including protein and lipid synthesis and degradation, gluconeogenesis and expression of Uncoupling proteins." (PMID 28177923, 2017). "In geriatric patients, cachexia is associated with higher-than-normal concentrations of tumor necrosis factor-α (TNF-α), interleukin (IL)-1, and IL-6; a reduction in these proinflammatory cytokines is associated with weight gain." (PMID 28254736, 2017). "In vivo and in vitro analysis of Lewis lung carcinoma-driven cachexia demonstrated decreased muscle ATP synthesis rates and decreased mitochondrial electron flow with associative increases in TNF-α." (PMID 28785374, 2017). "Earlier studies have shown that ApcMIN mice exhibit uncontrollable systemic elevations in inflammatory factors IL-6, IL-1b, and TNF-a, with these same factors also associated with cachexia in patients." (PMID 26933816, 2016). "Previous data showed cachexia and death in acutely T. cruzi-infected mice injected with the anti-TNF TN3 antibody and remarkable body weight loss in chronically infected hamsters treated with the TNF blocker Etanercept." (PMID 25140115, 2014). "Both cachexia and pre-cachexia are frequently associated with inflammation; an imbalance between pro-inflammatory (TNF-α, Interleukin (IL)-6, and IL-1) and anti-inflammatory (e.g., IL-4, IL-12, IL-15) cytokines is considered to contribute to the pathogenesis." (PMID 25988122, 2014). "Raised levels of Interleukin (IL)-1β, IL-6, Tumor Necrosis Factor-alpha (TNF-α) are implicated as tumor-derived factors in cachexia." (PMID 22361433, 2012). "We presently demonstrate a higher protein content for TNF-α and IL-1β in the hypothalamus of rats with anorexia-cachexia associated with cancer." (PMID 21861927, 2011). "Cytokines that have been implicated in the development of cachexia include IL-6, IL-1, TNFα, and interferon-gamma (IFN-γ)." (PMID 21832306, 2011). "High levels of serum TNF-α during the course of disease are usually associated with toxemia symptoms (anorexia, lethargy and cachexia) and high mortality rates." (PMID 20967289, 2010). "Around this same time, it was discovered that TNF-α was identical to cachectin, a mediator responsible for cachexia associated with sepsis." (PMID 19750096, 2009). "The acute LCMV disease has characteristics of starvation that resemble both cachexia (TNF-α or IL-6-mediated wasting) and anorexia (appetite loss)." (PMID 19216742, 2009). "BMAP-18 also inhibited secretion of TNF-α, an inflammatory cytokine that plays a role in the cachexia associated with African sleeping sickness." (PMID 19190729, 2009). "Sex‐dependent inflammation has been observed in other models of cachexia, and thus, increased lipolysis in males via upregulated levels of inflammatory cytokines like TNFα could be a mechanism of fat loss in our model." (PMID 41267538, 2025).